RACGAP1 (Rac GTPase activating protein 1)
Diseases named in the same sentence as RACGAP1 in open-access papers (continued):
Sharing a sentence is not in itself a finding about the gene and the disease.
ovarian carcinoma (15 papers, 2013 to 2025). A malignant neoplasm originating from the surface ovarian epithelium. "RACGAP1 plays a critical role in the progression and prognosis of epithelial ovarian cancer (EOC), predominantly expressed in the nuclei of tumor cells and associated with advanced tumor stages, high pathological grades, and lymph node metastasis." (PMID 39033780, 2024). "Regarding ovarian cancer, RACGAP1 was predicted to correlate with poor OS (p < 0.01) and progression-free survival (PFS) (p < 0.05), but not post-progression survival (PPS)." (PMID 36430577, 2022). "In ovarian cancer, it was found that RACGAP1 expression enhanced activation of RHOA and ERK proteins, and activation of its signaling induced cancer cell migration and invasion." (PMID 30866526, 2019). "This study establishes RACGAP1 as a novel, potent target for therapeutic intervention and necessitates further experimental and clinical evaluations to explore RACGAP1 inhibitors or modulators to improve ovarian cancer treatment strategies." (PMID 39033780, 2024). "In ovarian cancer, circASXL1 inhibited the miR-320d-mediated RACGAP1 downregulation." (PMID 39858398, 2024). "The pathophysiological process of ovarian cancer possibly involves RACGAP1." (PMID 39858398, 2024). "This in turn enhances RACGAP1 expression and activates the RACGAP1/PI3K/Akt axis, and subsequently, promotes ovarian cancer cell proliferation and invasion potentials." (PMID 40584294, 2025).
bladder cancer (9 papers, 2020 to 2025). "However, it is also reported that Rac1 inactivation caused by RACGAP1 can promote bladder cancer progression, in which the RACGAP1-SHCBP1 interaction is induced by EGF." (PMID 39858398, 2024). "In addition to bladder cancer, bioinformatics and machine learning also imply RACGAP1 involvement in the development of lung carcinoma-associated membranous nephropathy (MN)." (PMID 39858398, 2024). "For example, SHCBP1 enhances the migration and invasion of bladder cancer cells by inhibiting RACGAP1-mediated Rac1 inactivation." (PMID 40799237, 2025). "Together, these results imply that RACGAP1 expresses abnormally in various types of bladder cancers and probably in some other diseases of the urinary system." (PMID 39858398, 2024). "Considering the oncogenic role of RACGAP1 in the malignant behaviors of bladder cancer cells, we inferred that RACGAP1 exerts cancer-promoting functions via the upregulation of p-STAT3, active RhoA, and p-ERK1/2." (PMID 35013128, 2022). "In the urinary system, RACGAP1 is upregulated in bladder cancer." (PMID 39858398, 2024). "Moreover, Pleomorphic adenoma gene like-2 (PLAGL2) facilitated bladder cancer progression via RACGAP1/RhoA GTPase/YAP1 signaling, and its proproliferative and prometastatic effects were negated by the RhoA inhibitor simvastatin." (PMID 39101139, 2024). "RACGAP1 functions as an oncogenic protein in bladder cancer." (PMID 35013128, 2022). "The SHCBP1/RACGAP1/RAC1 interaction could therefore serve as a potential candidate for designing novel targeted therapeutic strategies for bladder cancer in clinical management." (PMID 35013128, 2022). "EGF stimulation increased the interaction between SHCBP1 and RACGAP1, which in turn attenuated the catalytic activity of RACGAP1 toward GTP-RAC1 in bladder cancer." (PMID 40789837, 2025). "In bladder cancer, nuclear translocation of SHCBP1 induced by EGF inhibits RACGAP1-mediated RAC1 inactivation to promote cancer cell proliferation and invasiveness." (PMID 40799237, 2025). "RACGAP1-mediated activation of RhoA can enhance the activity of YAP1/TAZ, thereby assisting PLAGL2 in promoting the progression of bladder cancer." (PMID 38898473, 2024). "RT-qPCR confirmed that RACGAP1 expression was elevated in bladder cancer tissues, and there was a significant positive correlation between SHCBP1 and RACGAP1 mRNA expression." (PMID 35013128, 2022). "RACGAP1 stimulates STAT3 phosphorylation and promotes its nuclear translocation, thus facilitating cell proliferation, migration, and decreased chemosensitivity to doxorubicin in bladder cancer." (PMID 35013128, 2022). "Compared with adjacent nontumor tissues, RACGAP1 expression was obviously upregulated in 19 paired bladder cancer tissues in the TCGA cohort." (PMID 35013128, 2022). "In this study, we found that cell movement is RAC1-dependent in bladder cancer, and RAC1 activity, but not RhoA and CDC42, is inhibited by RACGAP1, which is partially reversed following SHCBP1 ectopic expression." (PMID 35013128, 2022).
lung adenocarcinoma (9 papers, 2019 to 2025). A carcinoma that arises from the lung and is characterized by the presence of malignant glandular epithelial cells. "Overall, these data suggest that RacGAP1 may function as an oncogene in lung adenocarcinoma and that its expression is associated with an unfavorable prognosis and poor survival." (PMID 40497948, 2025). "Given the observed upregulation of RacGAP1 in LUAD patients and its association with prognostic factors and poor survival, the potential oncogenic role of RacGAP1 in lung adenocarcinoma was experimentally evaluated." (PMID 40497948, 2025). "In this study, we found that RacGAP1 was markedly upregulated in five different transcriptomic datasets of patients diagnosed with lung adenocarcinoma." (PMID 40497948, 2025). "We aimed to investigate the expression and clinic significance of Rac GTPase Activating Protein 1 (RACGAP1) in human lung adenocarcinoma (LUAD)." (PMID 38622149, 2024). "Therefore, in this study, we demonstrated for the first time that RacGAP1 plays a pivotal role in lung adenocarcinoma, contributing to the abnormal activation of the Wnt/β-catenin signaling pathway." (PMID 40497948, 2025). "Rac GTPase activating protein 1 (RacGAP1) has been found to be upregulated in several cancers, where it acts as an oncogene; nevertheless, its role in lung adenocarcinoma is largely unknown." (PMID 40497948, 2025). "We also analyzed the relationship between RacGAP1 expression and common lung adenocarcinoma driver gene state (mutated and non-mutated), in particular EGFR, ALK and K-RAS, finding no obvious and significant difference." (PMID 40497948, 2025). "However, there is little research on RACGAP1 in lung adenocarcinoma, so the role of RACGAP1 in lung adenocarcinoma is mainly studied." (PMID 38167018, 2024). "RACGAP1 was significantly upregulated in the high stemness score group of lung adenocarcinoma and closely correlated with clinical pathological features, poor overall survival (OS), recurrence-free survival (RFS), and unfavorable prognosis in lung adenocarcinoma patients." (PMID 38167018, 2024). "RACGAP1 overexpression possibly led to PI3K/AKT pathway activation and subsequently cell growth in lung adenocarcinoma." (PMID 39858398, 2024). "The expression of RACGAP1 was examined using Western blot in both normal lung epithelial cell line BEAS-2B and three different lung adenocarcinoma cell lines (A549, H1975, H1299)." (PMID 38167018, 2024). "Immunohistochemistry (IHC) demonstrated that mRNAs DLGAP5, MCM7, RACGAP1, and RRM2 were upregulated in lung adenocarcinoma (LUAD)." (PMID 32149133, 2020). "Further in animal experiments, it was found that decreased RACGAP1 expression significantly reduced tumor growth, suggesting that RACGAP1 plays a non-negligible role in the progression of lung adenocarcinoma." (PMID 38167018, 2024). "Although rescue experiments (e.g., RacGAP1 re-expression after silencing) were not performed, experimental results demonstrated the impact of RacGAP1 on cell proliferation, migration and invasion, thus supporting its oncogenic role in lung adenocarcinoma." (PMID 40497948, 2025).
cervical cancer (8 papers, 2019 to 2025). A primary or metastatic malignant neoplasm involving the cervix. "In cervical cancer, RACGAP1 is considered to be associated with the cell cycle and proliferation via CDC25C." (PMID 39858398, 2024). "In cervical cancer, it was exhibited that RACGAP1 could mediate c-Jun expression and phosphorylation." (PMID 39858398, 2024). "By controlling CDC25C, RACGAP1 encourages the growth of cervical cancer cells." (PMID 37391503, 2023). "In our study, RacGAP1 could increase the level of active RhoA, which in turn caused changes in the downstream effector ROCK1 in cervical cancer." (PMID 35831303, 2022). "Univariate and multivariate Cox regression analysis confirmed that the high RacGAP1 expression could be an independent predictor of poor survival in cervical cancer." (PMID 35831303, 2022). "Moving to other types of human tumors, RACGAP1 was able to promote melanoma transendothelial migration through mediating adherens junction disassembly and promoted proliferation and cell cycle progression by regulating CDC25C in cervical cancer cells." (PMID 36430577, 2022).
liver cancer (8 papers, 2019 to 2025). An epithelial or non-epithelial malignant neoplasm that arises from the liver. "Of note, it has been reported that RACGAP1 is overexpressed and associated with shorter overall survival in multiple malignances, including cancers of liver, gallbladder, breast, bladder and prostate." (PMID 38898473, 2024). "Aberrant expression of RACGAP1 had relationship with histologic grade (p = 0.031), Barcelona Clinic Liver Cancer stage (p = 0.017) and portal vein tumor thrombus (p = 0.041)." (PMID 35958019, 2022). "Not only the tumor stage but also tumor metastasis showed a positive correlation with RACGAP1 expression in breast, kidney, and liver cancers." (PMID 36430577, 2022). "Mechanistically, RACGAP1P acts as an endogenous sponge for miR-15-5p to prevent its association with RACGAP1, leading to activation of the RhoA/ERK signalling axis and enhancing liver cancer cell proliferation and migration." (PMID 31160556, 2019). "In uterine sarcoma and liver cancer, RACGAP1 activated the STAT3-survivin signaling pathway." (PMID 37196108, 2023). "Notably, data analysing of the TCGA data found that the RACGAP1 locus undergoes copy number gains in 13.2% liver cancers and the methylation level in the promoter region is lower in cancer tissues than normal tissues and negatively associated with RACGAP1 mRNA level." (PMID 31160556, 2019). "Altogether, PRC1 and RACGAP1 are identified both as prognosis markers for early HCC detection and therapeutic targets for liver cancer and liver CSCs, adding additional layers for the early prognosis and therapy of HCC." (PMID 35445033, 2022). "qPCR validation in normal liver and HCC tissues showed that CCNA2, CSRP2, ILF2, KIF2C, RACGAP1, and VARS were significantly upregulated in the HCC group (all p-values < 0.0001), providing more evidence for their role in liver cancer progression and potential as HCC biomarkers." (PMID 41323394, 2025). "Therefore, PRC1 and RACGAP1 are identified as prognosis markers for early HCC and therapeutic targets for liver cancer and liver CSCs." (PMID 35445033, 2022). "Finally, liver cancer demonstrated poor OS, disease-specific survival (DSS), PFS, and RFS (p < 0.001) with RACGAP1 expression." (PMID 36430577, 2022).
lung carcinoma (6 papers, 2018 to 2025). "In this study, after reducing RACGAP1 expression in lung cancer cells A549 and H1975 by using si technique, flow cytometry revealed that the expression of cell cycle-related proteins CDK2 and CDK4 was reduced." (PMID 38167018, 2024). "In summary, SMC6, CDC27, CDC7, RACGAP1, SMC4, NCF1,2,4, SELPLG and CFP are significantly associated with T2DM and lung cancer, making them potential target genes for disease prediction and treatment in the future." (PMID 38468345, 2024). "We then examined RACGAP1 expression in surgically resected tumors from 75 patients with lung cancer using immunohistochemistry (IHC)." (PMID 38622149, 2024). "The present study used bioinformatics analysis of online databases and tissue microarray (TMA) to evaluate the expression profile of RACGAP1 and the relationship between RACGAP1 expression and clinical pathological parameters in lung cancer." (PMID 38622149, 2024). "In summary, the current study analyzed RACGAP1 mRNA and protein expression in multiple cancers, including lung cancer, and determined their correlation with prognosis and clinicopathological features." (PMID 38622149, 2024). "By, cell scratch assay also further demonstrated that decreased RACGAP1 expression resulted in decreased lung cancer cell migration." (PMID 38167018, 2024). "The results demonstrated that the downregulation of RACGAP1 inhibited the migration, proliferation, and tumor growth of lung cancer cells." (PMID 38167018, 2024). "This study suggests recommends evaluating RACGAP1 in clinical settings as a novel biomarker and potential therapeutic target for lung cancer." (PMID 38622149, 2024). "Other genes, including PLK1, CDCA8, ANLN, and RACGAP1, were all discovered to play different roles in proliferation, metastasis, and enhanced chemotherapy sensitivity to doxorubicin in lung cancer." (PMID 35464867, 2022). "However, no detailed evidence has been available on the relationship between RACGAP1 and lung cancer diagnosis and prognosis, except for its upregulation in lung cancer." (PMID 38622149, 2024). "Overall, we found that RACGAP1 knockdown exerted anti-tumor activity in vitro, indicating that RACGAP1 might be involved in lung cancer development." (PMID 38622149, 2024). "Moreover, a series of experiments using representative lung cancer cell line were conducted to examine the functional role of RACGAP1." (PMID 38622149, 2024). "Moreover, RACGAP1 knockdown attenuated PI3K/AKT pathway activation in lung cancer cells." (PMID 38622149, 2024). "Taken together, our findings showed that RACGAP1 was overexpressed in LUAD tissues and played an important role in lung cancer by increasing cell growth through the PI3K/AKT signaling pathway." (PMID 38622149, 2024). "We found weak or no RACGAP1 expression in normal lung tissues but moderate and high RACGAP1 expression in lung cancer tissues." (PMID 38622149, 2024).
lymph node metastasis (6 papers, 2021 to 2024). "Rac GTPase activating protein 1, encoded by RACGAP1, functions as a GTPase-activating protein (GAP), and its overexpression is significantly associated with lymph node metastasis and poor prognosis in CRC86." (PMID 38167453, 2024). "The expression of RACGAP1 was also related to the number and extent of lymph node metastasis and the spread in the lymph node region." (PMID 36060002, 2022).
melanoma (5 papers, 2017 to 2022). A malignant, usually aggressive tumor composed of atypical, neoplastic melanocytes. "RacGAP1 contributed to this process as depletion of RacGAP1 or overexpression of a RacGAP1 mutant attenuates melanoma cell migration concomitantly with changes in adherens junctions." (PMID 30211160, 2018). "Moreover, Zhang and colleagues demonstrated that in endothelial cells RacGAP1, by activating RhoA, induced junction breakdown with consequent increase of permeability promoting melanoma cells transendothelial migration." (PMID 28680152, 2017).
prostate carcinoma (5 papers, 2023 to 2025). A carcinoma that arises from epithelial cells of the prostate gland. "The underlying mechanism is that RACGAP1 promotes the neuroendocrine transdifferentiation of prostatic cancer by stabilizing the expression of EZH2 in the ubiquitin proteasome pathway." (PMID 39048965, 2024). "MYBL2 overexpression has been shown to inhibit Hippo signaling by regulating expression of RACGAP1 leading to activation of YAP signaling in prostate cancer." (PMID 40115748, 2025). "Researchers have shown that the differentially expressed gene Rac GTPase-activating protein 1 (RACGAP1) is involved in the NE transdifferentiation of prostatic cancer." (PMID 39048965, 2024). "A prognostic model for prostate cancer takes RACGAP1 as one of its five key lactylation-related genes." (PMID 39858398, 2024). "Correlation between RACGAP1 mRNA expression and clinicopathological parameters of prostate cancer patients." (PMID 37196108, 2023). "RACGAP1 promoted neuroendocrine transdifferentiation of prostate cancer by stabilizing EZH2 expression in the ubiquitin-proteasome pathway." (PMID 37196108, 2023). "Through the analysis of the GRASSO prostate cancer database, we found that the expression of RACGAP1 was significantly increased in patients with PTEN, RB1, and E2F1 gene mutations, suggesting that E2F1 was related to RACGAP1." (PMID 37196108, 2023). "Our results showed that RACGAP1 promoted enzalutamide resistance of prostate cancer in vitro and in vivo." (PMID 37196108, 2023). "The corresponding function of RACGAP1 in prostate cancer was analyzed by CCK-8 and Transwell assays." (PMID 37196108, 2023). "In addition, a study on prostate cancer also reported the reciprocal promotion between RACGAP1 and androgen receptors (ARs)." (PMID 39858398, 2024). "It has been further suggested that RACGAP1 can promote the NED of prostate cancer." (PMID 37196108, 2023). "We confirmed that RACGAP1 contributed to NE transdifferentiation of prostate cancer." (PMID 37196108, 2023). "In addition, high RACGAP1 expression was correlated with poorer RFS of patients with prostate cancer." (PMID 37196108, 2023). "We investigated RACGAP1 expression in clinical prostate cancer specimens by IHC." (PMID 37196108, 2023).
squamous cell carcinoma (5 papers, 2019 to 2025). A carcinoma arising from squamous epithelial cells. "The E2F family can cause the overexpression of RACGAP1 in squamous cell carcinoma." (PMID 39858398, 2024). "Besides, RacGAP1 is implicated in the resistance to doxorubicin treatment in squamous cell carcinoma." (PMID 31426369, 2019). "Another study reported that the overexpression of RACGAP1 also predicts survival rates for squamous cell carcinoma." (PMID 40421085, 2025). "Consistently, RACGAP1 induced doxorubicin resistance in squamous cell carcinoma, resulting from the upregulated E2F7 binding to the RACGAP1 promoter." (PMID 39858398, 2024). "In squamous cell carcinoma, RACGAP1 was found to be regulated by the E2F7 transcription factor, and its expression enhanced doxorubicin resistance." (PMID 30866526, 2019). "RACGAP1 was also found to be a downstream effector of E2F7-dependent resistance to doxorubicin and a prognostic for OS in squamous cell carcinoma." (PMID 36430577, 2022).
uterine carcinosarcoma (5 papers, 2019 to 2025). A usually aggressive malignant neoplasm arising from the uterine corpus and less often the cervix. "In uterine carcinosarcoma cells, RACGAP1 positively regulated STAT3 phosphorylation and survivin expression, and these activated signaling pathways induced an invasive phenotype." (PMID 30866526, 2019). "Importantly, RACGAP1 was identified as a metastatic driver in uterine carcinosarcoma." (PMID 33252198, 2021).
Cirrhosis (4 papers, 2019 to 2024). A chronic disorder of the liver in which liver tissue becomes scarred and is partially replaced by regenerative nodules and fibrotic tissue resulting in loss of liver function. "Clinically, cirrhosis is one of the risk factors of HCC, the molecular mechanism of which may involve RACGAP1, as the recurrence-free survival and overall survival of the disease progression can take RACGAP1 as one of the independent prognostic factors." (PMID 39858398, 2024). "This study revealed that PRC1, RACGAP1, CENPF, and CCNB2 could sensitively distinguish HCCfrom cirrhosis, and they may be potential targets for early HCC detection." (PMID 35445033, 2022). "PRC1, RACGAP1, and CDCA5 were identified as the crucial genes in the pathological progression from cirrhosis to HCC, and their hypomethylation may drive the high expression of these genes." (PMID 33505422, 2020).